ARF1 (ARF GTPase 1)
Diseases named in the same sentence as ARF1 in open-access papers (continued):
Sharing a sentence is not in itself a finding about the gene and the disease.
neuroendocrine carcinoma (1 paper, 2015). A malignant neuroendocrine neoplasm composed of cells containing secretory granules that stain positive for NSE and chromogranin. "Taken together our data show that Arf1 has an important role in regulating Golgi structure and secretion in a model of neuroendocrine cancer." (PMID 25754106, 2015). "In summary, our data indicate an important regulatory role for Arf1 at the Golgi in hypersecretion in neuroendocrine cancer cells." (PMID 25754106, 2015).
parasite (1 paper, 2021). "The changes in Golgi morphology and subcellular location induced by the loss of GTPase activity (Arf1, Rab1a or Rab11a) and by the parasite infection were visualized by staining against the GM130." (PMID 34013963, 2021).
rheumatic heart disease (1 paper, 2025). An autoinflammatory condition following an infection with Group A Beta Hemolytic Streptococcus (GABHS), in which the heart is attacked by antibodies formed in reaction to a recent GABHS infection. "Rheumatic Heart Disease (RHD) is a condition characterized by structural and functional damage to the heart valves as a result of ARF1." (PMID 40796655, 2025).
squamous cell carcinoma (1 paper, 2016). A carcinoma arising from squamous epithelial cells. "Examples of these pathways include fatty acid biosynthesis and metabolism, cell proliferation and invasiveness of squamous cell carcinomas of the head and neck, the Arf1 and mTOR/P70S6K pathways." (PMID 27049860, 2016).
Stroke (1 paper, 2025). Sudden impairment of blood flow to a part of the brain due to occlusion or rupture of an artery to the brain. "In summary, inhibiting LRP1 induced ARF1‐K73la can promote mitochondrial transport and improve stroke prognosis." (PMID 40984037, 2025).
tuberculosis (1 paper, 2023). A chronic, recurrent infection caused by the bacterium Mycobacterium tuberculosis.
Yersinia infection (1 paper, 2018). "Of these factors, only ARF1 has previously been linked to T3SS-mediated processes; it is thought to facilitate insertion of the T3SS translocon during Yersinia infection but has not been linked to T3SS activity in EHEC." (PMID 29921669, 2018).
cancer (53 papers, 2015 to 2026). A tumor composed of atypical neoplastic, often pleomorphic cells that invade other tissues. "GTPase-activating proteins are important regulators of small GTPases; among these, ASAP1 stimulates GTP hydrolysis on Arf1 and is implicated in cancer progression." (PMID 41028713, 2025). "GTPase-activating proteins (GAPs) are important regulators of small GTPases with a wide range of cellular functions; among these, ASAP1 stimulates GTP hydrolysis on Arf1 and is implicated in cancer progression." (PMID 40470248, 2025). "ASAP1 is a multidomain Arf GTPase-activating protein (ArfGAP) that catalyzes GTP hydrolysis on the small GTPase Arf1 and is implicated in cancer progression." (PMID 39763923, 2024). "High expression of ARF1 in a variety of malignant tumors is associated with tumor progression and metastasis." (PMID 33408784, 2021). "ARF1 and RhoA have been implicated in some aspects of cancer development, including tumor cell invasion and proliferation (40, –, 45)." (PMID 34903051, 2021). "Since then, several reports have underlined the importance of the Arf1/EGFR axis in cancer cells progression." (PMID 31991585, 2020). "MDA-MB-231-derived MVs also contain RhoA and RhoC GTPases, which are upregulated in cancer and involved in invasion and metastasis, as well as ADP-ribosylation factor 1 (ARF1), which is associated with MV release and MMP-9 activity within MVs." (PMID 26601108, 2015). "Whether the converse, that is an increase in Arf1 levels, leads to enhanced sialylation usually associated with cancers requires experimental exploration." (PMID 35465326, 2022). "Thus, to establish the importance of AP-1/GGA2 in cancer progression the clathrin adapter-associated molecules, such as a small GTPase Arf1 that is necessary for membrane recruitment of AP-1, and several accessory proteins need to be investigated using human samples." (PMID 34799560, 2021). "The parallel between our TNBC results and prior studies in other cancers supports the notion that ARF1 is a conserved and druggable vulnerability across cancer types." (PMID 41465279, 2025). "Further research is needed to validate this approach in vivo and to explore the broader applicability of ARF1-targeted interventions across cancer types." (PMID 41465279, 2025). "Here, in the Drosophila stem cell tumor system, a screening of over 100 chemicals, modified based on Exo2, led to the discovery of two new potent small‐molecule inhibitors of Arf1 for cancer therapy, denoted as DU101 and DU102." (PMID 39225354, 2024). "The cancer promoting effects of ARF1, ARF3, ARF4 and ARF6 in individual cancers have been studied, only the role of ARF5 in cancer has not been reported." (PMID 38617932, 2024). "The small G protein Arf1 has been identified as playing a selective role in supporting cancer stem cells (CSCs), making it an attractive target for cancer therapy." (PMID 39225354, 2024). "In conclusion, the newly developed Arf1 inhibitors in this study show promise as a novel strategy for cancer immunotherapy." (PMID 39225354, 2024). "This effort led to the identification of DU101 and DU102 as two potent small‐molecule inhibitors of Arf1 for cancer therapy." (PMID 39225354, 2024). "Previous investigations have demonstrated that Arf1 is highly expressed in multiple human cancers, including breast cancer, hepatocellular cancer, colorectal cancer, and prostate cancer." (PMID 39872623, 2023). "After analyzing the top 20 proteins, ARF1 attracted our attention due to its oncogenic effect on cancer stem cells (CSCs) via the lipolysis pathway." (PMID 37452028, 2023). "Recent studies in cancer cell lines highlighted the important role of Arf-1 at the contact sites between ER and mitochondria, and how Arf-1 contributes to maintain mitochondrial morphology and function." (PMID 37358952, 2023). "Inhibition of ARF1 activity is a promising direction for cancer immunotherapy, therefore, we selected ARF1 for investigation." (PMID 37452028, 2023).
cancer (continued). "In mouse tumors, we previously found that Arf1 ablation in cancer stem cells promoted an IFN-γ-mediated antitumor immune response." (PMID 38239560, 2023). "We recently found that inhibition of the ADP-ribosylation factor 1 (Arf1)-mediated lipid metabolism not only kills cancer stem cells (CSCs) but also elicits an anti-tumor immune response." (PMID 39872623, 2023). "Our previous TCGA data analysis also found an inverse correlation between Arf1 expression and T-cell infiltration and activation as well as better survival probability in various human cancers." (PMID 39872623, 2023). "As for ARF1, published research work indicated that it can inhibit the infiltration and activation of T cells in many cancers." (PMID 37791813, 2023). "Accumulating evidence suggests that ARF1 plays a role in the migration and invasion of cancer cells." (PMID 35805075, 2022). "The ARF1-mediated stimulation of cancer cell proliferation is further corroborated by Gu and collaborators’ study, which provides evidence that ARF1 interacts with and activates PI3K, thus stimulating the phosphorylation of AKT." (PMID 35805075, 2022). "Emerging evidence supports that ARF1 can be used as an effective therapeutic target for cancer treatment 17, 41, 42, corroborating our current finding." (PMID 33408784, 2021). "Overexpression of ARF1 failed to increase p-ERK expression and cell proliferation in IQGAP1-deficient cancer cells, suggesting that IQGAP1 was essential for the biological function of ARF1 in cancer." (PMID 33408784, 2021). "ARF1 promotes cancer stem cell viability via lipid metabolism, and its ablation induces anti-tumor immune responses in mice." (PMID 32894165, 2020). "During the last decade, Arf1 has emerged as a key regulator of tumor proliferation in various cancers." (PMID 31991585, 2020). "We found that Arf1 was frequently amplified or overexpressed in the majority of cancer types examined." (PMID 31924786, 2020). "In the context of cancer, ARF1 has an important function in inter- and intracellular signaling, cell cycle regulation and DNA repair, as well as necrosis and apoptosis." (PMID 32426352, 2020). "Here, the authors show that targeting Arf1-mediated lipid metabolism in CSC induces cell death but also an immunogenic anti-cancer response." (PMID 31924786, 2020). "The expression/activation of Arf1 and its GEFs are often associated with cell proliferation, migration, and tumor-cell invasion in various cancers, and Arf1 and Arf/GEF complexes have thus been proposed as valuable candidate targets in cancer therapy." (PMID 31991585, 2020). "Although inactivating a subset of ARF1-GEFs has been very useful for assessing the ARF1 function, ARF1 inhibitors remain a daunting challenge to develop into anti-cancer and anti-inflammatory drugs." (PMID 27517156, 2016). "ARF1 and ARF6 are well characterized as crucial regulators for vesicular trafficking, and their roles have been implicated in the cancer progression." (PMID 27517156, 2016). "Confocal microscopy was then used to analyze the subcellular distribution of ARF1 in prostate normal and cancer cells." (PMID 27213581, 2016). "Real-time RT-PCR revealed elevated expression levels of ARF1 in cancer cells (MCF7, MDA-MB-231 and Hs578T) when compared to human MCF10A mammary epithelial cells." (PMID 27517156, 2016). "Next, we investigated ARF1 expression across various cancer types using TCGA data." (PMID 41465279, 2025). "The pan-cancer analysis indicated that ARF1 expression is altered in numerous malignancies." (PMID 41465279, 2025). "Consequently, the new Arf1 inhibitors present an auspicious strategy for cancer immunotherapy and are presently under evaluation for clinical trials in patients with advanced solid tumors." (PMID 39225354, 2024).
cancer (continued). "As far as we are aware, this new Arf1 inhibitor is the pioneering drug that activates a dual anticancer therapy by promoting cancer stem cell aging and anti‐tumor immunity and may lay the groundwork for additional therapeutics targeting this dual process." (PMID 39225354, 2024). "Arf1 upregulation is negatively correlated with the prognosis of patients with cancer." (PMID 39872623, 2023). "We found that the human gDNAs were significantly increased in the cytoplasm of mouse DCs that were co‐cultured with the Arf1‐ablated human DLD1 cancer cells in comparison with those in the cytoplasm of mouse DCs that were co‐cultured with the Scramble‐ablated human DLD1 tumor cells." (PMID 37786300, 2023). "Notably, Arf1 ablation in cancer cells induces mitochondrial defects, endoplasmic-reticulum stress, and the release of damage-associated molecular patterns (DAMPs), which recruit and activate dendritic cells (DCs) at tumor sites." (PMID 31924786, 2020). "Furthermore, TCGA data analysis shows an inverse correlation between Arf1 expression and T-cell infiltration and activation along with patient survival in various human cancers." (PMID 31924786, 2020). "Interestingly, several of the molecular players discussed (BAR proteins, TORC2, MGCs Arf1 and caveolae) are involved in different cancer scenarios, potentially through altered mechanical responses." (PMID 31431176, 2019). "Furthermore, deregulation of certain Arf family members, such as Arf1 and Arf6, enhances cancer cell invasion and metastasis by stimulating Ras-related C3 botulinum toxin substrate 1 (Rac1), paxillin, talin or focal adhesion kinase (FAK)." (PMID 30884855, 2019). "Arf1 overexpression stimulates tumor progression and invasion, thus the inhibition of this protein could be useful for restraining cancer progression." (PMID 30884855, 2019). "We next compared the expression levels of ARF1 in human prostate normal and cancer cell lines." (PMID 27213581, 2016). "In summary, we provide evidence that ARF1 is a key regulator of cancer progression." (PMID 26908458, 2016). "Since para- and autocrine factors are known to induce constitutive activation of signal transduction pathways in cancer cells, it was attractive to speculate that growth factor-dependent signals could mediate constitutive activity of Arf1." (PMID 25754106, 2015). "The inhibition of the Arf1-GEF interaction will be beneficial for cancer therapy." (PMID 26255816, 2015). "Mitochondrial fission regulator 2 (MTFR2), ADP-ribosylation factor 1 (ARF1), and the ovarian tumor-associated protease deubiquitinase 6 A (OTUD6A) are also significantly overexpressed in CRC tissues, suggesting their potential roles in mitochondrial dynamics and cancer progression." (PMID 40750884, 2025). "Importantly, prior work in other cancer models has shown that azelastine can directly bind ARF1 (DARTS-based target identification and SPR with low-nanomolar Kd; loss of binding in an ARF1 mutant), which is mechanistically congruent with our ARF1-dependency and GCA rescue in TNBC." (PMID 41465279, 2025). "Western blotting, WST-1, and colony formation assays indicated that, unlike parental cells, ectopic ARF1 expression could not increase p-ERK expression or cell proliferation in IQGAP1-knockout HCT116 and RKO cells, suggesting that IQGAP1 was essential for the ARF1 function in cancer." (PMID 33408784, 2021). "Consequently, Arf1 seems to be a very compelling target to limit cancer development and inactivating Arf1 may constitute a valuable chemotherapy strategy in this regard." (PMID 31991585, 2020). "Because our results suggest that high expression of ARF1 is associated with cancer cell invasiveness, we finally examined whether overexpression of this small GTP-binding protein could confer the ability of non-invasive cancer cells to form metastasis in vivo." (PMID 26908458, 2016).
cancer (continued). "The modulation of ARF1 and its downstream signaling, such as the PI3K-AKT pathway, establishes it as a pro-metastatic signaling hub in breast and other cancers." (PMID 41465279, 2025). "This study focused on the ARF1/ERK signaling pathway, which is crucial in the progression of various cancers." (PMID 39879476, 2025). "In this study, two new potent small‐molecule inhibitors of Arf1, identified as DU101 and DU102, for cancer therapy are introduced." (PMID 39225354, 2024). "We previously found that the Arf1-ACSL (acyl-CoA synthetase long chain)-mediated lipid metabolism sustains stem cells and cancer stem cells in Drosophila and mice." (PMID 38239560, 2023). "The Arf1 small G protein and its activator GBF1 regulate Golgi-ER retrograde trafficking during mitosis and in cancer cells, at least in part through phosphorylation of GBF1 by mitotic kinases." (PMID 29632863, 2018). "Interestingly, we observed that the knockdown of TMED2 had a more pronounced effect on ARF1 than on p-ERK, possibly due to the regulation of ERK via multiple pathways in cancer cells." (PMID 39879476, 2025). "While its siblings, such as ARF1 and ARF5, have been widely investigated for their contributions to intracellular trafficking and organelle function, ARF6 has quietly been making waves in the field of cancer research." (PMID 40275490, 2025). "The Ink4a–Arf1-independent cancer-promoting mechanism of Bmi-1 has not been fully elucidated and is beyond the scope of this study." (PMID 38141761, 2024). "ARFs family (ARF1, ARF3, ARF4, ARF5, ARF6) are generally highly expressed in Pan-cancer." (PMID 38617932, 2024). "The circuit is assembled when the Ras‐superfamily monomeric GTPase Arf1, and the heterotrimeric GTPase Giαβγ and their corresponding GAPs and GEFs are coupled by GIV/Girdin, a protein that is known to fuel aggressive traits in diverse cancers." (PMID 36856068, 2023). "In cancer cells, it has been shown that activation of ARF6 (ADP-Ribosylation Factor 6), ADP Ribosylation Factor 1 (ARF1), and small GTP-binding proteins lead to phosphorylation of the myosin side chain of myosin and contraction of actomyosin, permitting MV to detach from the membrane." (PMID 37781539, 2023). "In addition, the intracellular C-terminus of ephrin-B1, which was necessary to cancer invasion, was reported to manage the MMP8 liberation from cells through activating the cell trafficking regulator Arf1." (PMID 35884594, 2022). "For instance, ARF1, the most altered protein in Stage IV, has been shown to promote BC metastasis; PARP1 has also been demonstrated to enhance metastasis not only in BC but also in other cancer types." (PMID 35453681, 2022). "The regulation of human Arf1 GTPase activity by ArfGEFs that stimulate GDP/GTP exchange and ArfGAPs that mediate GTP hydrolysis has attracted attention for the discovery of Arf1 inhibitors as potential anti-cancer agents." (PMID 32144363, 2020). "Indeed, AGAP2, which acts on ARF1 and ARF5, promotes cancer cell survival, migration and invasion in gliobastomas." (PMID 32426352, 2020). "They show that ARF1 stimulates the maturation of invadopodia, the release of shedding microvesicles and the activity of matrix metalloproteinase-9 (MMP-9), which promotes the degradation of the extracellular matrix (ECM) and, consequently, cancer cells invasion." (PMID 35805075, 2022). "By examining the differential expression of RagC, Rheb, RalA, Rab1A, Rab5, and Arf1 in cancer tissues (n = 369) and non-cancer controls (n = 160), we showed that RagC and Arf1 but not Rheb, RalA, Rab1A or Rab5 were significantly elevated in cancer tissues." (PMID 36267578, 2022). "We found that the Arf1-low group had a significantly better survival probability than the Arf1-high group for a number of cancer types, suggesting that Arf1 is a negative prognostic factor for these tumors, with low Arf1 expression indicating a good prognostic outcome." (PMID 31924786, 2020).
cancer (continued). "Our findings that Arf1 inhibition stimulates T-cell infiltration and activation may provide a basis for therapeutic strategies that exploit DAMP-mediated anti-tumor immunity induced in cancer patients." (PMID 31924786, 2020). "Although the importance of the ARF1 gene has been determined using tail vein injection of immunocompromised SCID mice, intravascular injections only model extravasation and metastasis, and lack the growth characteristics and metastatic properties of human cancer." (PMID 27517156, 2016).